TRBV11-1 (T cell receptor beta variable 11-1)
Description:
V region of the variable domain of T cell receptor (TR) beta chain that participates in the antigen recognition. Alpha-beta T cell receptors are antigen specific receptors which are essential to the immune response and are present on the cell surface of T lymphocytes. Recognize peptide-major histocompatibility (MH) (pMH) complexes that are displayed by antigen presenting cells (APC), a prerequisite for efficient T cell adaptive immunity against pathogens. Binding of alpha-beta TR to pMH complex initiates TR-CD3 clustering on the cell surface and intracellular activation of LCK that phosphorylates the ITAM motifs of CD3G, CD3D, CD3E and CD247 enabling the recruitment of ZAP70. In turn ZAP70 phosphorylates LAT, which recruits numerous signaling molecules to form the LAT signalosome. The LAT signalosome propagates signal branching to three major signaling pathways, the calcium, the mitogen-activated protein kinase (MAPK) kinase and the nuclear factor NF-kappa-B (NF-kB) pathways, leading to the mobilization of transcription factors that are critical for gene expression and essential for T cell growth and differentiation. The T cell repertoire is generated in the thymus, by V-(D)-J rearrangement. This repertoire is then shaped by intrathymic selection events to generate a peripheral T cell pool of self-MH restricted, non-autoaggressive T cells. Post-thymic interaction of alpha-beta TR with the pMH complexes shapes TR structural and functional avidity.
Synonyms: TRBV111; TCRBV11S1; TCRBV21S1
Gene: T-cell receptor variable (V) gene on chromosome 7 (142,407,672 to 142,408,136, forward strand). Ensembl gene ENSG00000211720.
Subcellular location: Cell membrane
Gene Ontology:
Biological process: cell surface receptor signaling pathway
Cellular component: plasma membrane
Homologues: Orthologues: macaque TRBV11-1 (87% identical), mouse Trbv14 (66% identical). Paralogues in human: TRBV11-2 (85% identical), TRBV11-3 (80% identical), TRBV7-9 (65% identical), TRBV7-3 (64% identical), TRBV7-2 (62% identical), TRBV7-6 (62% identical), TRBV7-7 (61% identical), TRBV7-4 (58% identical), TRBV7-1 (57% identical), TRBV12-5 (57% identical), TRBV14 (53% identical), TRBV17 (52% identical), and 39 more.